TRAF2 (TNF receptor associated factor 2)
Diseases named in the same sentence as TRAF2 in open-access papers (continued):
Sharing a sentence is not in itself a finding about the gene and the disease.
atherosclerosis (8 papers, 2014 to 2025). A disease characterized by the build-up of fatty material and calcium deposition in the arterial wall resulting in partial or complete occlusion of the arterial lumen. "Only one study has tested the impact of TRAF2 in experimental atherosclerosis with TRAF+/− mice in bone marrow transplantations using TRAF2-deficient hematopoietic cells from fetal livers to generate viable mice with a deficiency of TRAF2 in hematopoietic cells." (PMID 35252400, 2022). "In the current paper, we investigated the role of B cell specific TRAF2- and NCK-interacting kinase (TNIK) in atherosclerosis." (PMID 37215541, 2023). "In these mice, atherosclerotic lesion size was similar to respective controls, suggesting that TRAF2 expressed in immune cells does not affect atherosclerosis." (PMID 35252400, 2022). "In addition, it was shown that TRAF2/3/5 signaling does not affect atherosclerosis or neointima formation." (PMID 36267276, 2022). "Likewise, disrupting TRAF-1, a negative inhibitor of TRAF-2, protected from atherosclerosis, while the genetic inhibition of TRAF-2 did not change atherosclerotic lesion burden." (PMID 28676852, 2017). "In another study, the lack of the TRAF2, TRAF3, and TRAF5 binding site on CD40 in MHCII+ cells did not interfere with neointima formation after arterial injury and atherosclerosis." (PMID 35252400, 2022). "Using mice with site-directed mutagenesis for the TRAF6 or TRAF2/3/5 binding site on the CD40 intracellular tail, we demonstrated that CD40-TRAF6 interactions, and not CD40-TRAF2/3/5 interactions, promote the development of atherosclerosis and neointima formation." (PMID 28494768, 2017).
mantle cell lymphoma (8 papers, 2016 to 2025). Mantle cell lymphoma is a rare form of malignant non-Hodgkin lymphoma affecting B lymphocytes in the lymph nodes in a region called the ``mantle zone''. "Recurrently occurring mutations in TRAF2 were also observed in mantle cell lymphoma resistant against the B-cell receptor (BCR) signaling inhibitor ibrutinib." (PMID 36011046, 2022). "Human mature B cell lymphomas, including multiple myeloma (MM), mantle cell lymphomas (MCL) or marginal zone lymphomas (MZL), frequently harbor mutations or deletions of TRAF2, TRAF3 or BIRC3 (a.k.a. cIAP2)." (PMID 37679334, 2023). "Because mutations in other NF-κB pathway genes, including BIRC3, TRAF2, TRAF3, MAP3K14 and CARD11, have been associated with ibrutinib resistance in mantle cell lymphoma, we next investigated whether mutations in NFKBIE could also affect the response to ibrutinib treatment." (PMID 38486128, 2024). "Notably, although not cataloged in TCGA, mutations of TRAF2 are recognized as one of the most frequent somatic mutations in mantle cell lymphoma (MCL, 6.1%, 10/165) and diffuse large B-cell lymphoma (DLBCL, 6%, 6/101)." (PMID 30294322, 2018). "In mantle cell lymphoma (MCL), resistance to ibrutinib (the BCR antagonist that targets Bruton’s tyrosine kinase) is characterised by aberrant non-canonical NF-kB signalling due to mutations in TRAF2 and BIRC3." (PMID 37835430, 2023).
Obesity (8 papers, 2017 to 2023). Accumulation of substantial excess body fat. "Among several inflammatory signaling pathways associated with obesity induced insulin resistance, TNFα signaling was induced by tumor necrosis factor-α receptor-associated factor 2 (TRAF2), activating JNK and IKK, which contributed to the development of insulin resistance." (PMID 33208918, 2020). "Although plasma cytokines such as BAFF and CD40L are significantly elevated in obesity, TRAF2 and TRAF3 are still highly expressed in the obese liver, which is likely due to the activation of their transcription." (PMID 35807520, 2022). "In obesity, key molecules in NIK signaling pathway such as BAFF, CD40L, TRAF2, TRAF3, NIK, and p52 are abnormally elevated." (PMID 35807520, 2022). "First, we identified gene sets related to the function of each obesity-related serum factor: HG/HI (Insr, Irs1, Rps6kb1, Slc2a4, Slc2a5, Slc2a1), TNF-α (Tnfrsf1a, Tradd, Traf2, Fadd), IL-6 (Il6ra, Il6st, Jak1), and fatty acids (PA, LA, Chol; Ffar1, Ffar4, Ppara, Pdk4, Pgc1a)." (PMID 37047207, 2023).
prostate carcinoma (8 papers, 2018 to 2025). A carcinoma that arises from epithelial cells of the prostate gland. "UPR activation in prostate cancer through the IRE1α pathway begins with the recruitment of TRAF2 by IRE1α which causes the activation of ASK1." (PMID 33773548, 2021). "Notably, the androgen receptor-independent transactivation of KHDC4 and TRAF2 by E2F4 was demonstrated using multiple prostate cancer cell lines and further validated through clinically relevant transcriptome datasets." (PMID 40560737, 2025). "TRAF2 has also been investigated as a prognostic biomarker for prostate cancer." (PMID 39061149, 2024). "TRAF2 has been shown to function as an oncogene in breast, gastric, and prostate cancers." (PMID 39061149, 2024). "Also, CPNE1 is significantly correlated with the tumor stage, Gleason score and recurrence-free survival of prostate cancer and is positively correlated with expression of TRAF2 as a prognostic marker in prostate cancer." (PMID 35139863, 2022). "Moreover, analysis of human prostate cancer datasets from TCGA (Cell, Firehose Legacy, and PanCancer) did not reveal a significant positive correlation between KHDC4 or TRAF2 and androgen receptor expression." (PMID 40560737, 2025).
Autoimmunity (7 papers, 2014 to 2026). The occurrence of an immune reaction against the organism's own cells or tissues. "This could be either due to the susceptibility of Nikaly/aly to autoimmunity that is exacerbated by the loss of TRAF2 or there could be another unknown pathway inhibited by TRAF2 that is worsened by NIK mutation." (PMID 26701909, 2015). "However, the clinical development of TRAF2 inhibitors should be accompanied by close monitoring for signs of autoimmunity or B-cell hyperplasia." (PMID 36011046, 2022). "The degradation of TRAF2, facilitated by FEM1B, plays a crucial role in moderating excessive immune responses, thereby helping to prevent autoimmunity." (PMID 40392678, 2025). "The lack of fine-tuning of TRAF2 activity leads to excessive NF-kB activation, driving chronic inflammation and autoimmunity." (PMID 40229245, 2025).
diffuse large B-cell lymphoma (7 papers, 2013 to 2025). "Similarly, inactivating mutations of TRAF2 have been identified in multiple myeloma and diffuse large B-cell lymphoma (DLBCL)." (PMID 23758787, 2013). "In addition, TRAF2 gene alterations are associated with diffuse large B-cell lymphoma (DLBCL)." (PMID 39061149, 2024). "Moreover, TRAF2 was characterized as a low-risk gene in Cervical squamous cell carcinoma and endocervical adenocarcinoma (CESC), lymphoid neoplasm diffuse large b-cell lymphoma (DLBC), and STAD (HR < 1, P < 0.05)." (PMID 38825674, 2024). "Beyond that, in other different tumors, such as prostate cancer, breast cancer, and diffuse large B-cell lymphomas (DLBCL), altered TRAF2 expression was significantly related to poor survival time." (PMID 32566659, 2020).
liver cancer (7 papers, 2018 to 2025). An epithelial or non-epithelial malignant neoplasm that arises from the liver. "We found that TRAF2 is highly overexpressed in human liver cancer tissues, and high TRAF2 expression is associated with worse pathological characteristics of HCC samples, especially tumor grades as well as with poor survival of patients." (PMID 37081115, 2023). "The goal of this study is to investigate potential dysregulation of TRAF2 and its biological function in liver cancer, and to elucidate the underlying mechanism, leading to validation of TRAF2 as an attractive liver cancer target." (PMID 37081115, 2023). "TRAF2 depletion inhibited growth and survival of liver cancer cells both in vitro and in vivo by causing p62 accumulation, which is partially rescued by simultaneous p62 knockdown." (PMID 37081115, 2023). "Genetic alterations of TRAF2 are detected in 1–2% of human liver cancers, including deletion, mutation and amplification (TCGA, PanCancer Atlas)." (PMID 30294322, 2018). "Taken together, our results demonstrated that TRAF2 plays a promoting role in growth and survival of liver cancer cells." (PMID 37081115, 2023). "To explore the potential partners of TRAF2 by which TRAF2 promotes the proliferation of liver cancer cells, we generated stable lines in HepG2 and Huh7 cells, expressing FLAG-tagged TRAF2." (PMID 37081115, 2023). "Given that p62 depletion only partially abrogated growth suppression of liver cancer cells by TRAF2 depletion, indicating the involvement of other signals, a subject for future investigation." (PMID 37081115, 2023). "Although both TRAF2 and p62 are highly expressed in liver cancer tissues, the nude mice xenograft model revealed that ectopic expression of p62 alone has a weak effect on the proliferation of liver cancer cells." (PMID 37081115, 2023). "Here, we reported TRAF2 is up-regulated in human liver cancer cell lines and tissues, and high TRAF2 expression is associated with a poor prognosis of HCC patients." (PMID 37081115, 2023). "In this study, we sought to identify potential proteins interacting with TRAF2 to elucidate the mechanism by which TRAF2 regulates growth and survival of liver cancer cells." (PMID 37081115, 2023). "Biological characterization of TRAF2 revealed that TRAF2 depletion significantly suppressed growth and survival of liver cancer cells in both in vitro cell culture and in vivo xenograft models." (PMID 37081115, 2023). "In summary, our study supports an oncogenic role of TRAF2 in promoting growth and survival of liver cancer cells." (PMID 37081115, 2023). "In conclusion, our study provides the proof-of-concept evidence that TRAF2 is a valid target for liver cancer." (PMID 37081115, 2023). "Since we identified p62 as a substrate of TRAF2, we next determined potential involvement of p62 in the growth and survival of liver cancer cells suppressed by TRAF2 knockdown/knockout." (PMID 37081115, 2023). "Taken together, it appears that ubiquitinated p62 by TRAF2 is responsible for mTORC1 activation, which further promotes the growth of liver cancer cells." (PMID 37081115, 2023). "Recently, RIPK1 has been proved to have anti-cancer effects, especially preventing proteasome degradation of TRAF2 to control the development of human liver cancer." (PMID 32368189, 2020). "Furthermore, using siRNA-mediated knockdown, we explored the potential role of TRAF2 in liver cancer cell biology." (PMID 40144665, 2025). "To this end, we first evaluated TRAF2 gene expression in liver cancer cell lines and HCC tissues." (PMID 37081115, 2023). "TRAF2 promotes the growth of liver cancer cells both in in vitro and in vivo." (PMID 37081115, 2023). "In this study, we revealed mechanistically the role of TRAF2 in liver cancer cells." (PMID 37081115, 2023). "Although TRAF2 is involved in a variety of tumors, its role in liver cancer remains elusive." (PMID 37081115, 2023). "Thus, our study validated TRAF2 as a therapeutic target for liver cancer therapy." (PMID 37081115, 2023).
liver cancer (continued). "Whether and how TRAF2 regulates the growth of liver cancer cells remains elusive." (PMID 37081115, 2023). "Cyld negatively regulates NF-kB, known to be one of the most important players in inflammation and liver cancer, and the MAPK signaling cascade by removing ubiquitin chains from signaling molecules, such as NEMO, TRAF2, TRAF6, TRAF7, TAK1 and RIP1." (PMID 37298191, 2023).
heart failure (6 papers, 2013 to 2024). Inability of the heart to pump blood at an adequate rate to meet tissue metabolic requirements. "Another group used a transgenic mouse modelto generate a dilated heart failure phenotype that expresses inflammatory geneTNF receptor-associated factor 2 (TRAF2)." (PMID 39484122, 2024). "For instance, while TRAF2 has a key role in the subnetwork, its loss results in inflammatory and cardiac failure phenotypes which would invalidate it as a target." (PMID 33746983, 2021). "Its role in causing myocardial dysfunction has been demonstrated where TNF-receptor-associated factor 2 (TRAF2) expression lead to heart failure, and this can be reversed after removal of inflammatory stimulus." (PMID 31023326, 2019). "It has been shown that transgenic mice expressing high levels of TRAF2 developed adverse cardiac remodeling and heart failure." (PMID 35096272, 2022). "However, overexpression of TRAF2 resulted in adverse cardiac remodeling and heart failure in mice." (PMID 39546553, 2024).
Insulin resistance (6 papers, 2013 to 2025). Increased resistance towards insulin, that is, diminished effectiveness of insulin in reducing blood glucose levels. "Concurrently, HGK deficiency in T cells induces the degradation of TRAF2, elevating IL-6 levels, which promotes Th17 differentiation and leads to insulin resistance." (PMID 40096134, 2025). "MAP4K4 deficiency has been reported to stabilize TRAF2 and induce TRAF2/IL-6 upregulation, leading to insulin resistance." (PMID 28101327, 2017). "MAP4K4 downregulates IL-6 production in T cells through direct phosphorylation and degradation of TNF receptor-associated factor 2 (TRAF2), leading to the suppression of Th17 cell-mediated insulin resistance in vivo." (PMID 36568222, 2022). "Since TRAF2 is one of the substrates of Ubc13, ER stress-mediated insulin resistance might be reduced in ubc13+/− mice." (PMID 27796312, 2016). "Furthermore, TRAF2-JNK is the third pathway in ER-associated apoptosis, which has been demonstrated to be vital in insulin resistance." (PMID 23671882, 2013).
non-small cell lung carcinoma (6 papers, 2013 to 2023). A group of at least three distinct histological types of lung cancer, including non-small cell squamous cell carcinoma, adenocarcinoma, and large cell carcinoma. "For example, UCHL3 contributes to non-small cell lung cancer cell growth by stabilizing TRAF2 (TNF receptor-associated factor 2)." (PMID 37740194, 2023). "More interestingly, an adaptive survival program is induced by EGFR inhibition, leading to rapid formation of the EGFR-tumor necrosis factor receptor-associated factor 2 (TRAF2)-receptor-interacting protein 1 (RIP1)-IKK complex to activate NF-κB in non-small cell lung cancer xenograft model." (PMID 36358633, 2022). "It has been determined that endogenous phosphorylated TRAF2 and ribosomal protein S3 confer resistance to irradiation-mediated death of non-small cell lung cancer (NSCLC) cells." (PMID 27234396, 2013). "We recently revealed that a small-molecule Traf2 and Nck-interacting kinase (TNIK) inhibitor, NCB-0846,30 suppressed the EMT and metastasis of non-small cell lung cancer cells through post-translational modification of actinin-4 (unpublished observation)." (PMID 32265507, 2020).
cervical carcinoma (5 papers, 2019 to 2024). A carcinoma arising from either the exocervical squamous epithelium or the endocervical glandular epithelium. "The inhibitory effects of GSTP1-1 on TRAF2 were shown in human cervical cancer cells, where overexpression of GSTP1-1 suppressed TRAF2-induced activation of both JNK and p38." (PMID 37189435, 2023). "TNF also interacts physically with the TNF receptor TRAF2, as shown in a cervical cancer cell line." (PMID 31681304, 2019). "The overexpression of GSTP1 suppressed TRAF2-induced activation of both JNK and p38 as well as attenuating autophosphorylation of ASK1 and inhibiting TRAF2-ASK1-induced apoptosis in HeLa human cervical cancer cells." (PMID 39125992, 2024). "According to The Human Protein Atlas (THPA), TRAF2 has the highest expression in HNSCC, followed by cervical cancer among all sampled cancer types (17 cancer types)." (PMID 36142875, 2022).
diabetes (5 papers, 2007 to 2022). "This raises the possibility that protective islet TNFR2/TRAF2 signaling may confer resistance to islet destruction and diabetes." (PMID 17254331, 2007). "Then, we observed that diabetes remarkably enhances the expression levels of p-ASK1, p-JNK1/2, p-FoxO3a, and TRAF2 in the hippocampus." (PMID 32766246, 2020). "The authors conclude that diabetes susceptibility is not only determined by the immune system but also by the susceptibility of the target tissue to destruction and suggests that protective islet TNFR2/TRAF2 signaling may result in resistance to islet destruction and diabetes." (PMID 17254331, 2007). "All of these factors may eventually lead to neuronal apoptosis, and IRE1α, TRAF2, ASK1, JNK, caspase-12, PERK, CHOP, and caspase-3 were activated in this study, indicating that ERS was induced by diabetes." (PMID 34079471, 2021). "The abundance of p-IRE1α, TRAF2, and p-ASK1 in ASK1 immunoprecipitates was significantly increased in the hippocampus of db/db mice compared to those in db/m mice, indicating that diabetes enhances the formation of IRE1α–TRAF2–ASK1 complex in the hippocampus." (PMID 32766246, 2020).
ischemic stroke (5 papers, 2015 to 2022). A stroke disorder caused by obstruction of blood flow to the brain, due to thrombotic (local blood clot formation) or embolic (due to a blood clot or other material traveling from another site) event. "SNHG15 markedly impaired inflammatory responses through interference with TRAF2 auto-ubiquitination in the acute stage of ischemic stroke." (PMID 34980176, 2022). "Therefore, a phosphodiesterase 4 (PDE4) inhibitor can suppress apoptosis in ischemic stroke by interrupting the binding of IRE1α and TRAF2." (PMID 34824669, 2021). "We explored various in vitro and in vivo ischemia/reperfusion models and confirmed that γ-GC reduced ischemic stroke injury by inhibiting apoptosis via the PERK-eIF2α-CHOP and IRE1α-TRAF2-JNK axes." (PMID 34824669, 2021). "Furthermore, transcriptome analysis suggested that γ-GC relieved ER stress in ischemic stroke, and we confirmed that γ-GC inhibited neuronal apoptosis mediated by the PERK-eIF2α-CHOP and IRE1α-TRAF2-JNK axes." (PMID 34824669, 2021). "Proteomic analysis suggested that the differential expression of CALB2 during a global ischemic stroke could be involved in the mechanisms of ER stress-induced neuronal cell apoptosis, which occurred via IRE1-alpha/TRAF2 complex formation, with activation of JNK1/2 and p38 MAPK." (PMID 26016499, 2015).
lung adenocarcinoma (5 papers, 2014 to 2026). A carcinoma that arises from the lung and is characterized by the presence of malignant glandular epithelial cells. "A549 lung adenocarcinoma cells overexpressing mutant KEAP1 showed high TRAF2-mediated NFκB activity and increased protection against apoptosis, XIAP being one of the key proteins involved in anti-apoptotic signalling." (PMID 38184997, 2024). "There was a downregulation of most of necroptosis-related genes in lung adenocarcinoma (LUAD) versus lung tissues but an increase in PGAM5, HMGB1, TRAF2, EZH2 levels." (PMID 37965055, 2023).